IL27 (interleukin 27)
Diseases named in the same sentence as IL27 in open-access papers (continued):
Sharing a sentence is not in itself a finding about the gene and the disease.
autoimmune disease (continued). "A study on adipose-derived mesenchymal stem cells (AD-MSCs) created genetic engineered MSCs to release IL-27, so that they could be used for reduction of inflammation and, ultimately, as therapy in autoimmune diseases." (PMID 36009412, 2022). "IL-27 signaling could promote type 1 immune responses and directly limit IL-17 immunity, mitigating autoimmune diseases." (PMID 36330425, 2022). "IL-27 mediates inflammatory effects in autoimmune diseases such as SS and rheumatoid arthritis." (PMID 36389806, 2022). "However, data on the assessment of sirtuin 1 and IL-27 in relation to CV parameters in autoimmune diseases are limited." (PMID 34439776, 2021). "IL-27 can exert both pro-inflammatory and anti-inflammatory effects, which is currently being considered in novel therapeutic approaches for cardiovascular and autoimmune diseases." (PMID 34439776, 2021). "Although there has been gradually increased evidence of IL-27 being an immunosuppressive cytokine in various experimental infection and autoimmune disease models, it is unclear as to the exact role of IL-27 and its effect on retinal autoreactive T cell responses in EAU." (PMID 34299138, 2021). "Interestingly, Interleukin-27 (IL-27) possesses a dual function or pleiotropic, as anti- or pro-inflammatory properties, in a variety of autoimmune diseases such as MS." (PMID 32251441, 2020). "An anti-inflammatory function of IL-27 has been reported in several autoimmune diseases; however, in type 1 diabetes (T1D), an autoimmune disease where autoreactive cytotoxic T cells attack insulin-producing beta cells, IL-27 has been shown to have a dual role and contradictory effects." (PMID 31949260, 2020). "Previous studies have suggested that IL-27 is another key modulator of autoimmunity and elevation of IL-27 signaling may be inhibitory to some autoimmune diseases, such as multiple sclerosis or uveitis." (PMID 31988799, 2020). "And IL-27 limited autoimmune disorders by promoting Tr1 cells." (PMID 32849596, 2020). "IL-27 has anti-inflammatory properties during autoimmune diseases." (PMID 28738904, 2017). "Thereby, the efficacy of treatment with IL-27 to autoimmune diseases in which IL-27 Th17 cells participate may be insignificant." (PMID 27869736, 2016). "Our results confirm those obtained in earlier studies in experimental autoimmune disease models in which IL-27 was shown to play a role as a master negative regulator in both EAE and EAU by suppressing the development of Th1 and Th17 cells and promoting the development of Tr1 cells." (PMID 24887071, 2014). "Thus, understanding the role of IL-27 in NK cell function has important implications for treatment of autoimmune disorders." (PMID 22039443, 2011). "Our results suggest that IL27 signalling may be a therapeutic target against autoimmune diseases, including human SLE." (PMID 18094002, 2008). "Although we need further characterization of 27-Mac to determine whether the cells are the converted M1 macrophages, IL-27 may regulate the M1/M2 polarizing ratio, which affects the development of autoimmune disease or tumor and immunoregulation and therapeutics." (PMID 40129989, 2025). "Furthermore, given the relationship of IL-27 with inflammatory autoimmune diseases, IL-27 may not only inhibit autoimmunity development but also promote the pathogenesis of autoimmune diseases." (PMID 40724937, 2025). "In autoimmune diseases like rheumatoid arthritis, structural variations in IL-12 family cytokines (e.g., IL-23-driven IL-17 cascade) disrupt the immune balance, affecting leukocyte migration, bone erosion, and angiogenesis, while IL-12, IL-27, and IL-35 exert counter-regulatory effects." (PMID 40519922, 2025). "Thus, IL-27 may serve as a potential cytokine-based therapy for various viral infections and autoimmune diseases, and cancer progression." (PMID 40129989, 2025).
autoimmune disease (continued). "Therefore, IL-27 gene polymorphisms may indeed change the mRNA and protein expression of IL-27, which is involved in the pathogenesis of different autoimmune diseases." (PMID 38566992, 2024). "Furthermore, An IL-27-producing innate B-1a cell (i27-Breg), which accumulates and is maintained in the CNS and lymphoid tissues during neuroinflammation, exerts a protective effect against CNS autoimmune diseases." (PMID 39076985, 2024). "In addition, in vivo delivery of recombinant IL-27 by different approaches, including protein infusion pump, as well as lentiviral and adeno-associated virus packaging, have been used to confirm the therapeutic effect of IL-27 in suppressing experimental autoimmune diseases." (PMID 34299138, 2021). "Interleukin 27 could limit autoimmune diseases by stimulating IL-10–secreting T cells." (PMID 32849596, 2020). "Overall, our data show that IL-27 is a key cytokine in antigen-induced peripheral tolerance and may provide basis for improvement of antigen-specific tolerance approaches in multiple sclerosis and other autoimmune diseases." (PMID 29163476, 2017). "Altogether, these observations highlight the pivotal role of IL-27 in induction of peripheral tolerance in autoimmune inflammation and provide a basis for future therapeutic approaches aiming to induce tolerance in patients with MS and other autoimmune diseases." (PMID 29163476, 2017). "Thereforeoverexpression of IL-27 may be a good optionalth erapy against autoimmune diseases." (PMID 24611150, 2014). "Recent studies have also shown that IL-27 is involved in anti-inflammatory functions, especially interfering with TNF-α or TH17 cells (or both) in autoimmune diseases, including multiple sclerosis, rheumatoid arthritis, and systemic lupus erythematosus." (PMID 22827855, 2012). "More recent reports have described the capacity of IL-27 to suppress TH17 cells by inhibiting TH17 cell differentiation, thereby reducing severity of TH17-mediated autoimmune diseases." (PMID 22827855, 2012). "The IL-27-regulated differentiation and function of peripheral CD4+ T cells subsets Th1, Th17, and Treg have been proposed as an explanation for the pathogenesis of autoimmune disease, however, conflicting reports have been demonstrated in different settings." (PMID 40366856, 2025). "IL-27 is a unique cytokine with reported immunostimulatory and immunosuppressive effects that are exerted through STAT1/3-dependent cascades and thought to be involved in various autoimmune diseases including T1D." (PMID 41027725, 2025). "This study not only uncovers IL-27 as a critical modulator of MSC immune plasticity but also provides a foundation for developing IL-27-enhanced MSC2 as an innovative therapeutic modality applicable to LN and other autoimmune disorders." (PMID 40642057, 2025). "Unlike the stimulation of tumor immunity, IL-27 is often suggested as a therapeutic option in autoimmune diseases because it has anti-inflammatory effects." (PMID 39063193, 2024). "The exact mechanisms by which IL-27 contributes to the pathogenesis of these autoimmune diseases require further investigation because results from experimental models of autoimmune diseases have shown contradictory and not fully defined dual roles of IL-2720." (PMID 31949260, 2020). "Dendritic cells are thought to be the main source of IL-27 in non-infectious conditions, such as autoimmune diseases and cancer." (PMID 29033934, 2017). "Among pathways shared by any two groups, we find the IL pathways are informative for shared disease features: the IL23 and IL27 pathways are common to both autoinflammatory and mixed diseases, while the IL2 pathway is common to both autoinflammatory and autoimmune diseases." (PMID 27964755, 2016). "Moreover, Th17 and some cytokines such as IL17, IL21, IL27, IL35, and IL37 are recognized well in autoimmune diseases, though their possible roles as therapeutic target in GBS need to be further explored." (PMID 25614713, 2014).
autoimmune disease (continued). "Rag1−/− mice failed to induce type 1 diabetes, which confirmed that the lack of IL-27 could prevent the occurrence of autoimmune diseases." (PMID 36389806, 2022). "In addition, IL-27 can also increase the content and ratio of Th1 and Th17 cells, thus leading to the excessive secretion of inflammatory mediators in local tissues, such as IFN-γ, CXCL10, and TNF-α, Thereby forming an inflammatory cascade that eventually induces autoimmune diseases." (PMID 34691022, 2021).
Sepsis (64 papers, 2012 to 2026). Sepsis is defined as life-threatening organ dysfunction caused by a dysregulated host response to infection. "For human studies, a meta-analysis showed that IL-27 is a good diagnostic biomarker for sepsis both in pediatric and adult settings." (PMID 40429966, 2025). "For instance, the interleukin (IL)-27-964A > G polymorphism enhances IL-27 expression, thereby promoting an inflammatory response induced by sepsis and ultimately leading to sepsis progression and poor prognosis." (PMID 38716051, 2024). "The effects of IL-27 in sepsis also relied on IL-27 gene polymorphisms: the IL27 -964A > G polymorphism increased the expression of IL-27 and exacerbated inflammatory responses in sepsis, leading to the advancement of sepsis and a negative outcome." (PMID 39063193, 2024). "IL-27 has been identified to participate in the pathology of sepsis, and elevated IL-27 can be detected in the serum of septic patients early after the onset of sepsis, which is considered as a diagnostic biomarker of sepsis." (PMID 35013123, 2022). "The results of our study clearly demonstrated that IL-27 was an accurate diagnostic biomarker for sepsis with the potential for clinical applicability." (PMID 33954170, 2021). "The present results showed that IL-27 is a reliable diagnostic biomarker of sepsis, but it should be investigated in combination with other clinical tests and results." (PMID 33954170, 2021). "Gene expression studies have shown that transcripts from sepsis and severe viral infections involve pathways associated with signaling through TLRs, IL-27, IL-12, IFN-γ, type I IFN-inducible transcripts, and the JAK-STAT pathway." (PMID 34659208, 2021). "While it is apparent that IL-27 has clear association with immune dysfunction during sepsis, there is still more to be learned about the exact role of IL-27 in the context of sepsis." (PMID 34079555, 2021). "The present study was aimed to investigate the value of blood interleukin-27 (IL-27) as a diagnostic biomarker of sepsis." (PMID 33954170, 2021). "The relationship between IL-27 genetic polymorphisms (rs153109/-964A and rs17855750/2905) and sepsis has also been studied." (PMID 34079555, 2021). "The pooled AUC was 0.88 (95% CI, 0.84-0.90), suggesting that IL-27 is a highly accurate diagnostic biomarker for sepsis." (PMID 33954170, 2021). "Studies have shown that IL-27 also links up with suppression of inflammation and that IL-27 is a therapeutic target for limiting neonatal susceptibility to sepsis and improving infection outcomes." (PMID 33954170, 2021). "Elevated levels of IL-17 and IL-27 are found in the serum of pediatric and adult septic patients early after sepsis onset and have been proposed as diagnostic biomarkers." (PMID 31507598, 2019). "In septic patients and in murine models of sepsis, the plasma concentration of IL-27 significantly increases, briefly causing it to be considered as a potential diagnostic biomarker in adults and children." (PMID 31507598, 2019). "A total of 80 patients with sepsis and 80 healthy individuals were randomly selected to evaluate the possible associations between the IL-27 rs153109 or rs17855750 polymorphisms and IL-27 expression in PBMCs." (PMID 30268141, 2018). "Accumulating evidence has demonstrated that the IL-12 family member IL-27 is pivotal in the pathogenic mechanisms of sepsis." (PMID 30268141, 2018). "In this study, for the first time, we investigated the association between sepsis and two functional polymorphisms (rs153109 and rs17855750) in the IL-27 gene." (PMID 30268141, 2018). "The purpose of this study was to evaluate the clinical relevance of IL-27 genetic polymorphisms in sepsis and to further characterize their effect on IL-27 expression and inflammatory processes following sepsis." (PMID 30268141, 2018).
Sepsis (continued). "In this study, for the first time, we provided evidence indicating a significant association between the IL-27 polymorphism and the progression of sepsis in a Chinese Han population." (PMID 30268141, 2018). "We prospectively tested the diagnostic utility of IL-27 as a sepsis diagnostic biomarker in a heterogeneous cohort of critically ill children." (PMID 26514771, 2015). "Loss of IL-27 signaling improves the survival rate in an experimental murine neonatal sepsis model." (PMID 40977737, 2025). "However, several studies have demonstrated that IL-27 is a poor choice for a prognostic biomarker in sepsis-associated conditions." (PMID 39063193, 2024). "IL-27 emerges as a pro-inflammatory factor and mediates a variety of pro-inflammatory biological activities implicated in the pathogenesis of inflammation-related diseases, including sepsis." (PMID 35013123, 2022). "In our previous study, we found IL-27 is elevated in sepsis and sepsis-associated liver injury patients and animal models, which is related to the proinflammatory factors and the severity of sepsis, and promoted liver injury." (PMID 33564275, 2021). "Several studies have reported elevated serum IL-27 levels during sepsis, suggesting that IL-27 could potentially be a diagnostic biomarker of sepsis." (PMID 34079555, 2021). "Therefore, this meta-analysis was the first to make a judgment about the diagnostic accuracy of IL-27 in sepsis and to evaluate the associated specificity and sensitivity." (PMID 33954170, 2021). "In summary, our results suggest that elevated levels of IL-27 early in life predispose the host to impaired control of the pathogen burden, which is further compounded by continued increases in circulating levels of IL-27 during sepsis." (PMID 31818960, 2020). "As T cell dysfunction and exhaustion is associated with the development of immunosuppression during sepsis and ultimately worsened survival, IL-27 could be an effective therapeutic target." (PMID 31507598, 2019). "The results of an in vitro (lipopolysaccharide (LPS))-stimulated experiment showed that this sepsis-associated high-risk AA genotype significantly increased IL-27 levels and enhanced TNF-α and IL-1β production in the peripheral blood mononuclear cells (PBMCs) upon exposure to LPS in vitro." (PMID 30268141, 2018). "Other studies have indicated that elevated IL-27 strongly correlates with early-onset sepsis and might provide additional diagnostic value for sepsis, alone or in combination with PCT." (PMID 30268141, 2018). "Furthermore, functional in vitro assays were performed to characterize the effect of these IL-27 variants on its gene expression and inflammatory processes following sepsis." (PMID 30268141, 2018). "We performed luciferase assays using different types of cells to evaluate the effect of the − 964 A-to-G variation on the promoter activities of the IL-27 gene and confirmed that the sepsis-associated A risk allele of rs153109 significantly increased the promoter activity in 293 T and THP-1 cells." (PMID 30268141, 2018). "It has been reported that IL-27 plays an anti-inflammatory role in septic mice and contributes to the sepsis-induced immuno-suppression, blockading the biological function of IL-27 results in increased survival and reduces the susceptibility to secondary P. aeruginosa infection." (PMID 27994590, 2016). "Recent studies suggest interleukin-27 (IL-27) as another candidate sepsis diagnostic biomarker." (PMID 26514771, 2015). "In our study population, PCT concentrations were not significantly different between patients with SIRS and patients with sepsis; and IL-27 generally performed better than PCT as a diagnostic biomarker based on the AUC and the test characteristics calculated for various cut points." (PMID 23107287, 2012).
Sepsis (continued). "To better understand the involvement of IL-27 in host immune responses to S. aureus osteomyelitis, we measured IL-27 in serum from healthy individuals, orthopedic patients with culture-confirmed S. aureus bone infections, and patients who died from sepsis associated with S. aureus osteomyelitis." (PMID 36028492, 2022). "Hence, it is biologically feasible to use IL-27 as a diagnostic marker for sepsis." (PMID 33954170, 2021). "Following sepsis and secondary intrapulmonary challenges with P. aeruginosa, neutralization of IL-27 significantly improves survival of septic mice and clearance of P. aeruginosa; conversely, direct application of recombinant IL-27 increases susceptibility to P. aeruginosa infection." (PMID 33276561, 2020). "In addition, other functional polymorphisms may interfere with IL-27 expression, and these integrated effects should be studied for better estimation of individual risk of the onset or development of sepsis." (PMID 30268141, 2018). "Presence of sepsis and older age influenced the level of IL-27 (interaction 3% p=0.056; age p=0.009; sepsis presence p>0.0001)." (PMID 39935482, 2025). "As such, in the present study, we investigated the role of STAT-3 signaling in IL-27-mediated suppression of bacterial clearance and lysosomal activity in neonatal macrophages during in vitro infection and sepsis." (PMID 40130859, 2025). "While enhancing early inflammatory responses, IL-27 paradoxically suppresses Th1/Th17 differentiation and potentiates IL-10 production from Tregs and type 1 regulatory T (Tr1) cells during late-phase sepsis." (PMID 40364841, 2025). "The most prominent cytokines in sepsis related immunosuppressive were IL-4, IL-10, IL-27, IL-37, IL-38 and TGF-β." (PMID 40364841, 2025). "IL-27, a dual-functional member of the IL-12 cytokine family, modulates sepsis pathogenesis through cell-type-specific actions on macrophages, DCs, and lymphocytes." (PMID 40364841, 2025). "IL-27 is known to play a role in the immune response during sepsis; serum levels are elevated during the neonatal period and increase further upon infection." (PMID 40977737, 2025). "Overall, a profile of IL-27 producers was suggestive of failed coordination and dysregulation of the immune system that typifies sepsis." (PMID 40682363, 2025). "Serum concentration of IL-27 has also been shown to be higher in patients with sepsis-related acute hepatic injury compared to septic patients without liver injury." (PMID 40429966, 2025). "After IL-27 signal blockade by a newly synthesized protein, the survival rates in murine models of sepsis increased." (PMID 39063193, 2024). "In bacterial infections, especially those that are often followed by sepsis, IL-27 is usually elevated in the blood plasma." (PMID 39063193, 2024). "We opted for a ready-made reagent kit for cytokine analysis, which led to the omission of several well-recognized cytokines associated with sepsis progression, such as CXCL-1, IL-18, IL-26, and IL-27." (PMID 38707899, 2024). "Cytokine IL-27 has been identified as a pro-inflammatory factor in the pathology of sepsis, which is primarily released by dendritic cells and macrophages." (PMID 37711624, 2023). "One study reported outcomes of IL-27 in the detection of sepsis, the sensitivity was 0.96 (95% CI: 0.85, 1.00; I2 = NA, p = NA) and the pooled specificity was 1.00 (95% CI: 0.92, 1.00; I2 = NA, p = NA), respectively." (PMID 38027268, 2023). "Two studies reported outcomes of IL-27 in the detection of sepsis, the pooled sensitivity was 0.80 (95% CI: 0.72, 0.87; I2 = 94.0%, p = 0.001) and the pooled specificity was 0.74 (95% CI: 0.65, 0.82; I2 = 28.0%, p = 0.239), respectively." (PMID 38027268, 2023). "The detection performance of IL-27, IL-8, and IL-10 in late-onset sepsis ranked from superior to inferior based on the superiority index." (PMID 38027268, 2023).